RUNX1 (RUNX family transcription factor 1)
Diseases named in the same sentence as RUNX1 in open-access papers (continued):
Sharing a sentence is not in itself a finding about the gene and the disease.
tumor (continued). "Interestingly, RUNX1 expression in COAD was higher than in normal samples, suggesting a poor prognosis in these patients, which seems to be inconsistent with the role of tumor suppressors in gastrointestinal malignancies." (PMID 35534796, 2022). "First, we tested the effects of the Runx1 molecular inhibitor (Runx1i) with and without Smoi in our mouse tumor organoid model." (PMID 36473848, 2022). "Several genes associated with metastatic spread were upregulated in hybrid cells relative to unfused tumor cells, including activated leukocyte cell adhesion molecule (ALCAM), runt-related transcription factor 1 (RUNX1), and fms-related tyrosine kinase 4 (FLT4)." (PMID 36010865, 2022). "It has been shown that RUNX1 regulates EMT and inhibits tumor progression." (PMID 32549768, 2020). "The average phospho-pRb (Ser-807/811) levels were 2.7% in tumor tissues with reduced RUNX1 expression and 2.1% in tumor tissues without reduced RUNX1 expression." (PMID 32498288, 2020). "In this study, RUNX1 was found to be abnormally methylated at the CpG island of RUNX1 in NSCLC tumor tissues, and the methylation and mRNA levels of RUNX1 showed a linear negative correlation." (PMID 32498288, 2020). "RUNX1 and p-SMAD3 are key genes that promote tumor progression and EMT24,25." (PMID 31754093, 2019). "A search and verification of downstream targets revealed that RUNX1 plays a major role in the malignant progression of Mes GBM, affecting the formation of extracellular matrix through MGP and promoting the ability of tumor cells (especially cancer stem cells) to invade into normal tissues." (PMID 31754093, 2019). "Moreover, RUNX1 activated the Wnt/β-catenin signalling pathway to promote EMT and tumour metastasis." (PMID 31370857, 2019). "Expression levels of lncRNA-NEF and RUNX1 were significantly and reversely correlated in tumor tissues but not in adjacent healthy tissues." (PMID 31015363, 2019). "NPM1, RUNX1, and CEBPA are all genes from common genomic gains observed in a meta-analysis of copy number alterations across a panel of different cancer cell lines and tumor samples." (PMID 29738475, 2018). "RUNX1 and RUNX3 were originally considered as tumor suppressors." (PMID 27007162, 2016). "In fact, regression analysis using the Cox’s proportional Hazards model confirmed that RUNX1 has prognostic value together with tumour size and lymph node status in the TNBC subgroup." (PMID 24967588, 2014). "If RUNX1 has a pro-oncogenic role in TNBCs, the question arises as to why this effect is not observed in tumours expressing the oestrogen receptor." (PMID 24967588, 2014). "Interestingly, we discovered that two of the most highly expressed ACC target genes, VCAN and HAPLN1, can bind within a predicted ECM complex in ACC tumor cells and, in the case of HAPLN1, appear to be regulated by RUNX1 activation." (PMID 25587024, 2014). "Only RUNX1 and TET2 may be inactivated in the two-hit fashion that corresponds to "classical" tumor suppressors." (PMID 20678218, 2010). "Mechanistically, RUNX1 was a transcriptional suppressor of PLCL1, LCOR could interact with RUNX1 to relieve RUNX1-mediated repression of PLCL1, leading to increased PLCL1 expression, which, in turn, inhibited the tumor progression and lipid accumulation in ccRCC." (PMID 40083699, 2025). "Our study unveiled a potential molecular mechanism for the development of ccRCC, demonstrating that LCOR could interact with RUNX1 to relieve RUNX1-repressed PLCL1 transcription, leading to the upregulation of PLCL1 expression, which inhibited the tumor progression and lipid accumulation in ccRCC." (PMID 40083699, 2025). "Importantly, macrophage‐specific genetic deletion and systemic pharmacological inhibition of TGF‐β1/Smad3/Runx1 signaling effectively prevent MMT‐driven CAF and tumor formation in vitro and in vivo, representing a potential therapeutic target for clinical NSCLC." (PMID 37967345, 2024).
tumor (continued). "The role of RUNX1 as an oncogene vs. tumor suppressor is still not entirely clear and may depend on the type of malignancy, as well as other mutations present." (PMID 38968069, 2024). "Hence, we boldly speculate that a combined anti-RUNX1 and anti-PDGF-BB treatment may inhibit tumor angiogenesis and growth more effectively than single treatment in CRCs with high expression of RUNX1." (PMID 38419056, 2024). "Though AML with RUNX1::RUNX1T1 patients were used as an example to explore, we also obtained consistent conclusions in other AML subtypes, suggesting that ADGRG1 could become a potential unified marker of CD8+ tumor-reactive T cells within AML." (PMID 39243082, 2024). "Therefore, our results indicated the existence of tumor-reactive T cells (pTRTs and pTRT-relevant cells) in the BM of AML patients carrying the RUNX1::RUNX1T1 which showed a continuous spectrum of differentiation from the stem-like cluster to the terminally differentiated cluster." (PMID 39243082, 2024). "Bioluminescence images revealed that significant differences in tumor volume between U251 and GBM1 cells overexpressed USP10 displayed a significant induction of tumor growth compared with xenografts transduced with vector, and the effects were reversed by RUNX1 knockdown." (PMID 36949071, 2023). "In this study, RT-qPCR was used, a sensitive method for detection of fusion genes in tumor samples that conventional methodologies detecting even a single molecule in lower amounts of complex samples as bone barrow, which supports the low prevalence of ETV6::RUNX1 obtained." (PMID 35685921, 2022). "Related transcription factor-1 (RUNX1) is a transcriptional factor that controls the transcription of thousands of genes involved in tumour progression, as well as angiogenic and nonangiogenic tumour vascularization, including vessel co-option." (PMID 35267627, 2022). "Furthermore, potentially new candidate drivers of pancreatic carcinogenesis, like RUNX1 and ROBO2, could also be found in the tumor." (PMID 33764904, 2021). "Similarly, an increase in the susceptibility to AML development in conjunction with MLL-ENL and N-Ras in the absence of RUNX1 supported the role of RUNX1 as a tumor-suppressor." (PMID 33353065, 2020). "In summary, our results highlight a crucial role for RUNX1 in the regulation of tumour metastasis in CRC by activating the Wnt/β-catenin signalling pathway and EMT, and RUNX1 might be regarded as a potential prognostic marker and as an effective therapeutic target for CRC." (PMID 31370857, 2019). "Besides Pmp22, it is highly possible that other RUNX1/3 targets, such as SDC4, ERN1, and/or MBP, might be involved in tumor formation." (PMID 31032403, 2019). "Consequently, the N-t and RD truncates, like RUNX1 can perhaps take part in pathways, such as FOXO in the absence of TGF-β, while in the presence of TGF-β, beside FOXO pathway, can play a weaker role in tumor-promoter arm of TGF-β." (PMID 29201108, 2017). "Thus these findings have identified a novel function for Runx1 in sustaining normal epithelial morphology and preventing EMT and suggest Runx1 levels could be a prognostic indicator of tumor progression." (PMID 28407681, 2017).
tumor (continued). "The lack of a negative effect of RUNX1 mutations and total number of mutations also indicates that azacitidine may have specific biological effects on the MDS tumor clone." (PMID 26959885, 2016). "We immunostained the TMA to define each tumour as positive or negative for RUNX1 and AXIN1." (PMID 26916619, 2016). "In accordance to previous studies suggesting a tumor-suppressor role of Runx1, we found that the increased number of SkBr3 and HepG2 cells in S/G2/M phases upon exposure to E2 is no longer evident in cells overexpressing Runx1." (PMID 26030000, 2015). "Therefore, a comprehensive understanding of the role of Runx1 in various aspects of tumor biology, including MMT‐driven CAF formation, angiogenesis, and immune cell regulation, is essential for the development of effective therapeutic strategies targeting Runx1." (PMID 37967345, 2024). "In addition, we found that the expression of RUNX1, CDC20 and MCM2 correlated with the infiltration of tumor immune cells through bioinformatics analysis, and their expression may cause the tumor immune cells to be exhausted, and the possible mechanism of action remains to be investigated." (PMID 38886545, 2024). "However, the modulation mechanism of RUNX1 on ER stress in tumor cells has not been reported yet." (PMID 37697370, 2023). "Furthermore, the IHC analysis showed that the level of RUNX1 protein was also decreased in the circ7379 overexpression plasmid-treated group compared to the control group, indicating that ectopic circ7379 effectively reduced PDX tumor growth by blocking RUNX1 expression." (PMID 37564198, 2023). "Furthermore, the MDSCs in the peripheral blood and tumor tissues in the mice treated with both miR-21 antagomir and sh-NC inhibited Th and CTL proliferation compared with that in the mice treated with both antagomir NC and sh-NC, which was relieved by the addition of sh-RUNX1." (PMID 33061847, 2020). "However, the regulatory effects of lncRNA-NEF on RUNX1 in IHCC is likely mediated by disease-related factors due to the factor that expression levels of lncRNA-NEF and RUNX1 were only positively correlated in tumor tissues but not in adjacent healthy tissues of IHCC patients." (PMID 31015363, 2019). "Furthermore, multivariate analysis indicated that RUNX1 expression was independent of the established pathological prognostic factors currently used in the clinic making it a new putative prognostic indicator for TN tumours." (PMID 24967588, 2014). "We also found that transcription factor RUNX1 and gene PITPNC1 were highly expressed along the trajectory to tumor cells but not on the path to more differentiated epithelial cells." (PMID 40470730, 2025). "Furthermore, higher RUNX1 levels observed in RRMM patients, despite stable overall expression across ISS stages, suggests that RUNX1 may be reactivated or maintained during disease recurrence, possibly contributing to reshaping of transcriptional networks to favor tumor persistence." (PMID 40990016, 2025). "E2F7 cooperated with CBFB-recruited RUNX1 in a non-canonical manner to transactivate ITGA2, ITGA5, and NTRK1, strengthening Akt signaling-induced tumor-promoting effect." (PMID 37028765, 2023). "This modulation is also observed in RNA-seq of HCI-009, an AR+ PDX tumor grown in mice with or without DHT, which showed significant upregulation of RUNX1 (fold change = 1.84, p = 1.27 × 10−3)." (PMID 36766786, 2023). "Statistically significant differences in co-expression of PRMT1 with ZEB1, RUNX1 and TWIST1 were observed only in ccRCC, but not in other analyzed tumor types." (PMID 31655611, 2019).
tumor (continued). "In this sense, inhibition of the AP‐1, SMAD3 and RUNX1/RUNX2 pathways, in combination or not with the chemotherapeutic agent temozolomide, led to the subtype‐specific impairment of tumour growth, particularly in the context of the aggressive, mesenchymal‐like subtype." (PMID 37357610, 2023).
cancer (318 papers, 2010 to 2026). A tumor composed of atypical neoplastic, often pleomorphic cells that invade other tissues. "Recently, it was reported that RUNX1 expression is associated with immune infiltrates of cancer-associated fibroblasts in several types of cancers, including cervical; however, its role has not been fully studied in CC, and therefore, we focus on this gene." (PMID 41020879, 2025). "Additional investigation into how the presence of the ETV6/RUNX1 translocation impacts the adenoviruses ability to modulate cellular genes associated with cancer progression is of great interest." (PMID 41497616, 2025). "Different RUNX1 translocations have been described in various hematological malignancies, the RUNX1T3/CBFA2T3 fusion being the fifth most frequent partner in cancer-associated RUNX1 rearrangements." (PMID 38443661, 2024). "RUNX1, for example, regulates gene expression in hematopoiesis and has been implicated in several cancers." (PMID 39578854, 2024). "RUNX1 is a pivotal transcription factor implicated in the regulation of metastasis across various cancer types." (PMID 38430423, 2024). "Increased levels of RUNX1 positively correlate with the abundance of cancer-associated fibroblasts (CAFs) derived from MMT and with patient mortality." (PMID 39201328, 2024). "Cluster 1 genes enrichment was for just one GO term, transcription regulator complex, and included genes for the cancer-associated transcription factors RUNX1, HOXA9, and MYB." (PMID 38165902, 2024). "Deletions and somatic mutations of RUNX1 have also been associated with poor differentiation of malignant tumors." (PMID 36831308, 2023). "Observed expression of RUNX1 was higher in cancer tissues than normal tissues, which was linked with a significantly shorter survival." (PMID 37697370, 2023). "RUNX1 is a master transcription factor commonly mutated in multiple cancers, with particularly high frequency in hematologic malignancies and breast, colon, and lung carcinomas." (PMID 37581927, 2023). "The overexpression of RUNX1 in human malignancies was significantly associated with the prognosis of patients with cancers such as mesothelioma, lung squamous carcinoma, and stomach adenocarcinoma." (PMID 37444447, 2023). "RUNX1 is associated with various types of cancer, especially hematological malignancies and cancers of epithelial origin." (PMID 37760803, 2023). "According to Cancer Genome Atlas Network (2012) and the analysis performed by Caldas Group, the RUNX1 gene is mutated only in Luminal A/B tumors." (PMID 36766786, 2023). "RUNX1 is highly expressed in cervical cancer, and its overexpression is associated with a poorer outcome and stronger invasive ability of cancer cells through induction of EMT." (PMID 37444447, 2023). "RUNX1 expression was markedly linked to the prognosis of 11 cancer types (including OS and DFS) and had a detrimental effect on the corresponding tumors." (PMID 35534796, 2022). "This RUNX1-ETS model is helpful in addressing how cancer mutations play roles in DNA mediated allosteric functions and RUNX1-DNA binding." (PMID 36090034, 2022). "These residues are in proximity with cancer-associated mutations and are also located at the DNA binding interface of RUNX1." (PMID 36090034, 2022). "We also took 13 cancer-associated published drug compounds to model their possible binding to the transcription factor RUNX1." (PMID 36090034, 2022). "We retrieved cancer-associated mutations to identify those with the potential to alter RUNX1: DNA interactions." (PMID 36090034, 2022).
cancer (continued). "In the cancerous state, we observe T cell exhaustion, RUNX1-regulated cancer-associated fibroblasts and increasing accessibility associated with HNF4A motifs in epithelia." (PMID 35726067, 2022). "The S2d SFs also express Lrrc15, a recently identified marker for cancer-associated fibroblasts (CAFs) and activated fibroblasts and the TF Runx1." (PMID 35879783, 2022). "Docking of wild type RUNX1 with these 13 different cancer-associated drugs indicates that wild-type RUNX1 has a lower efficiency of binding while RUNX1 mutants R142K, D171N, R174Q, P176H, and R177Q suggested higher affinity of drug association." (PMID 36090034, 2022). "In our study, we first analyzed the association between immune infiltration and RUNX1 expression in human cancers using TIMER 2.0." (PMID 35534796, 2022). "Bioinformatic data revealed that RUNX1 is overexpressed in cancer, and its overexpression was also linked to a worse prognosis." (PMID 36077723, 2022). "Here, defined cancer-associated missense mutations of RUNX1 (R80C, R142K, D171, R174Q, P176H, and R177Q) are predicted to be relevant for DNA binding, and additionally in some cases, to drug binding." (PMID 36090034, 2022). "Our team reported the molecular signaling of cancer cell motility in vessel co-opting lesions, which are mainly associated with RUNX1 and ARP2/3 overexpression." (PMID 35267627, 2022). "Specifically, we analyzed 46 recurrent cancer associated missense mutation sites for RUNX1 within its DBD." (PMID 36090034, 2022). "One or more alterations were detected in 33 types of human cancers, and 9.5% (19 cases) of patients with AML (200 cases) were observed to have mutations in RUNX1, representing the highest frequency among all patients with cancer." (PMID 35534796, 2022). "RUNX1 expression was positively correlated with infiltrating levels of cancer-associated fibroblasts (CAFs) in 33 different cancers." (PMID 35534796, 2022). "In our study, we systematically explored the effect of RUNX1 expression on the prognosis associated with several human cancers." (PMID 35534796, 2022). "Bioinformatics data indicated that RUNX1 was overexpressed in most of these human malignancies and was significantly associated with the prognosis of patients with cancer." (PMID 35534796, 2022). "Here, we combined molecular modeling and docking as tools to predict the molecular-interaction consequences of cancer-associated missense mutations of RUNX1 to binding DNA, as well as to binding defined drugs." (PMID 36090034, 2022). "RUNX1 has been associated with various types of cancers, particularly hematological malignancies and cancers of epithelial origins." (PMID 36430923, 2022). "Accordingly, the cancer cells of vessel co-opting lesions were characterized by high expression levels of RUNX1, which was associated with an increased motility and EMT." (PMID 35267627, 2022). "Mutations are also found in a variety of cancers: loss of function mutations in T-cell acute lymphoblastic leukemia suggests a role for RUNX1 as a suppressor in T-cell transformation; somatic mutations were also detected in breast cancer." (PMID 36005134, 2022). "Further, we propose that molecular modeling and docking studies for RUNX1 in the presence of DNA and/or drugs enables evaluation of the potential impact of RUNX1 cancer associated mutations in AML." (PMID 36090034, 2022). "Our work, together with that of others, suggests that molecular mutation modeling and docking will prove useful for understanding the molecular consequences of RUNX1 cancer associated mutations." (PMID 36090034, 2022). "The upregulation of RUNX1 in the cancer cells is also associated with hepatocyte displacement and replacement by cancer cells in CRCLM, which are required for the development of vessel co-option." (PMID 36330498, 2022). "A significant amount of data on Aml1/Runx1 mutations and cancers and the relationship between Aml1/Runx1 overexpression and poor prognosis have been reported." (PMID 34440820, 2021).